TRPM7 (transient receptor potential cation channel subfamily M member 7)
Diseases named in the same sentence as TRPM7 in open-access papers (continued):
Sharing a sentence is not in itself a finding about the gene and the disease.
neuroblastoma (continued). "Moreover, microarray-based expression profiling on control and TRPM7 shRNA transduced neuroblastoma cells indicates that TRPM7 controls a developmental transcriptional program involving the transcription factor SNAI2." (PMID 25797249, 2015). "In addition, by gene expression profiling we demonstrate that TRPM7 is required for the maintenance of a progenitor-like gene expression program in human neuroblastoma cell lines." (PMID 25797249, 2015). "Future studies will determine how alterations in cytoskeletal dynamics affect the expression of SNAI2, and whether TRPM7-driven SNAI2 expression contributes to neuroblastoma progenitor-like features." (PMID 25797249, 2015). "Hence, our results strongly suggest that TRPM7 maintains stem cell features of neuroblastoma cells by expression regulation of SNAI2." (PMID 25797249, 2015). "To address if TRPM7 contributes to the malignant properties of neuroblastoma cells, we assessed whether TRPM7 overexpression promotes metastasis formation of poorly metastatic murine N1E-115 neuroblastoma cells in vivo." (PMID 25797249, 2015). "The presence and regulation of TRPM6 in SHEP-21N cells thus would suggest that this channel may also serve a role in the pathological context of neuroblastoma by regulating cellular Mg2+ levels in conjunction with TRPM7." (PMID 25277194, 2014). "Our results reveal that TRPM7 is essential for neuroblastoma proliferation and the additional expression of TRPM6 modulates the phenotype of native MagNuM currents, favoring divalent cation transport mediated by TRPM6 and TRPM7 and promoting neuroblastoma cell proliferation." (PMID 25277194, 2014). "In addition, in the largest publicly available neuroblastoma expression profiling dataset, the Kocak-649 cohort, TRPM7 mRNA expression is found in all tumor samples, and is significantly correlated to N-Myc amplification." (PMID 25277194, 2014). "Furthermore, treatments with isoproterenol decreased the expression of Bax and increased expression of Bcl2, suggesting that TRPM7 expression and function are modulated via isoproterenol, which is essential for the neurotoxin-induced survival of neuroblastoma cells." (PMID 32390858, 2020). "Importantly, overexpression of TRPM7 inhibited MPP+-mediated cell death of neuroblastoma cells." (PMID 32390858, 2020). "In neuroblastoma cells, bradykinin-induced activation of TRPM7 mediates Ca2+ influx in a kinase-independent manner and Ca2+ entry in macrophages triggered by lipopolysaccharide (LPS) is controlled by TRPM7, as observed in a cell-specific deletion model using a Cre/Lox system." (PMID 30995736, 2019). "Hence, we hypothesized that TRPM7 may preserve progenitor-like, metastatic features of neuroblastoma cells." (PMID 25797249, 2015). "Hence, we hypothesize that TRPM7 expression and/or activity may contribute to neuroblastoma progression by disrupting normal neural crest cell maturation and preserving progenitor-like features in tumor cells." (PMID 25797249, 2015). "However, neither in the Kocak dataset nor in the other datasets did TRPM7 expression associate with neuroblastoma disease stage, an important prognostic marker." (PMID 25797249, 2015). "Hence, TRPM7 may drive neuroblastoma metastasis by preserving neural crest-like progenitor features." (PMID 25797249, 2015). "The expression patterns of TRPM6 and TRPM7 in MYCN-amplified neuroblastoma cell lines and SHEP-21N cells suggests that their expression might not necessarily relate to N-Myc expression, as some MYCN-amplified cell lines had low TRPM6 expression levels (data not shown)." (PMID 25277194, 2014). "In a human neuroblastoma cell line, the MYCN oncogene has been reported to increase TRPM7 expression and thereby tumor cell proliferation and migration." (PMID 38255793, 2024).
neuroblastoma (continued). "Although the mechanisms involved in TRPM7-mediated protection of neuronal cells is not clear, an increase in pro-apoptotic proteins along with a decrease in ATP levels could be the major reason for the loss of neuroblastoma cells." (PMID 32390858, 2020). "Since TRPM7 was shown to be required for the development of neural crest derived tissues by maintaining the pool of pluripotent progenitor cells, we hypothesized that TRPM7 may contribute to neuroblastoma metastasis by preserving progenitor-like, migratory neural crest cell features." (PMID 25797249, 2015). "To see if and how TRPM7 affects viability and proliferation of MYCN-negative and positive neuroblastoma cells, we generated stable TRPM7 knockdown SH-EP2 and SH-SY5Y cells using a previously characterized lentiviral shRNA construct." (PMID 25797249, 2015). "al. observed a strong correlation between TRPM7 and MYCN expression levels in a large neuroblastoma patient cohort (Kocak, n = 649)." (PMID 25797249, 2015). "In order to investigate the role of N-Myc in TRPM7/TRPM6 regulation, we chose the SHEP-21N cell line, a clone derived from the SHEP-2 neuroblastoma, in which N-Myc is constitutively expressed but can be experimentally repressed." (PMID 25277194, 2014). "Given the role of Mg2+ in cell proliferation, the present study carefully examined two Mg2+-transporting channel kinases, TRPM7 and TRPM6, in neuroblastoma cells." (PMID 25277194, 2014). "A subsequent study revealed that TRPM7 enhanced metastatic potential, but not the proliferation rate in mouse neuroblastoma cells." (PMID 38255793, 2024). "Indeed, we confirmed by quantitative RT-PCR that expression of SNAI2 was reduced upon TRPM7 knockdown in both SH-SY5Y and SH-EP2 neuroblastoma cells." (PMID 25797249, 2015). "Moreover, genes that have previously been established to drive neuroblastoma progression and migration, including DBH, NOTCH1, RET and WNT1, were down regulated in response to TRPM7 knockdown." (PMID 25797249, 2015). "Although TRPM7 overexpression did not affect proliferation of mouse N1E-115 neuroblastoma cells, others have suggested a role for TRPM7 in neuroblastoma cell proliferation, specifically in a MYCN-amplified context." (PMID 25797249, 2015). "The TRPM7 modulation of invadosomes was reported to be independent of calcium influx for mouse neuroblastoma cells." (PMID 25946314, 2015). "Note that the progressive increase in bioluminescence was comparable in both groups, suggesting that the in vivo proliferation rate of neuroblastoma cells was not affected by TRPM7 expression levels." (PMID 25797249, 2015). "Moreover, overexpression of TRPM7 in the SNAI2 negative N1E-115 mouse neuroblastoma cell line induced expression of SNAI2." (PMID 25797249, 2015). "Moreover, we find an increased number of tumors in mice injected with mouse neuroblastoma cells that overexpress TRPM7, rather than increased tumor size." (PMID 25797249, 2015). "Hence, we conclude that TRPM7 enhances the metastatic potential, but not proliferation rate, of N1E-115 neuroblastoma cells in vivo." (PMID 25797249, 2015). "Collectively, genetic or pharmacological suppression of TRPM7/TRPM6 channels inhibits cell proliferation, underscoring the importance of these channels in promoting proliferation and pointing towards a potential therapeutic avenue for the treatment of neuroblastoma." (PMID 25277194, 2014). "The data presented in this study suggest that TRPM7 channels have a significant impact on cell proliferation of neuroblastoma, regardless of whether or not they express N-Myc, whereas additional TRPM6 expression further synergizes with TRPM7 in augmenting the proliferative activity." (PMID 25277194, 2014). "From these experiments, we conclude that in our hands, stable knockdown or overexpression of TRPM7 does not affect viability and proliferation of both MYCN-negative and MYCN-amplified neuroblastoma cell lines." (PMID 25797249, 2015).
neuroblastoma (continued). "However, using neuroblastoma cells that express more physiological levels of MYCN, we find that TRPM7 knockdown and overexpression do not affect proliferation in vitro, irrespective of MYCN amplification status." (PMID 25797249, 2015).
ovarian carcinoma (21 papers, 2016 to 2025). A malignant neoplasm originating from the surface ovarian epithelium. "TRPM7 has been reported to be highly expressed in ovarian cancer and significantly associated with poor prognosis, tumor progression and decreased disease-free survival in a Chinese population." (PMID 38255793, 2024). "As a result, TRPM7 overexpression is associated with poor prognosis in ovarian cancer patients as well." (PMID 36158191, 2022). "Given that lower E-cadherin but higher Vimentin and Twist expression are hallmarks of EMT process in cancer our data indicated that up-regulated TRPM7 expression was associated with the EMT process of ovarian cancer." (PMID 30819230, 2019). "However, the mechanisms underlying the action of TRPM7 in ovarian cancer are unclear." (PMID 30819230, 2019). "Specifically, TRPM7 contributes to metabolic reprogramming in bladder, ovarian cancer and hepatocellular carcinoma and TRPM8 in hepatocellular carcinoma." (PMID 40813985, 2025). "In conclusion, these findings suggest a regulatory mechanism in which TRPM7 modulates cellular metabolic shifts in ovarian cancer by influencing the AMPK/HIF-1α signaling pathway, highlighting its role as a key mediator in metabolic reprogramming." (PMID 40813985, 2025). "The important role of TRPM7 in metabolic reprogramming, especially in glycolytic pathway was also explored in the ovarian cancer." (PMID 40813985, 2025). "A subsequent study has revealed that TRPM7 mediates cell proliferation, migration and invasion in human ovarian cancer cell lines at least in part by influencing Akt, Src and p38 signaling pathways and the formation of cell adhesion complexes." (PMID 38255793, 2024). "TRPM7 expression correlates negatively with E-cadherin, but positively with N-cadherin, vimentin and Twist expression in human ovarian cancer cells." (PMID 38255793, 2024). "TRPM7 silencing suppressed the proliferation of ovarian cancer cells by shifting glycolysis to oxidative phosphorylation." (PMID 38255793, 2024). "Of interest, we found that TRPM7 KO suppresses both glycolysis and oxidative phosphorylation in T24 & HUVECs, in contrast to the observation that TRPM7 knockdown inhibited glycolysis but enhanced TCA in ovarian cancer cell." (PMID 36878949, 2023). "While our study is underway, a most recent study employed TRPM7 knockdown approach for in vitro assays, and reported that TRPM7 knockdown dampened ovarian cancer cell glycolysis via AMPK activation and HIF1 degradation." (PMID 36878949, 2023). "Compared with the control, TRPM7 silencing suppressed the proliferation of ovarian cancer cells by shifting preferable glycolysis to OXPHOS." (PMID 35101076, 2022). "In ovarian cancer, TRPM7 promotes the phosphorylation of Akt, Src and p38 and induces EMT via Twist1 expression." (PMID 36158191, 2022). "To test the functional outcomes of TRPM7 silencing, we quantified the proliferation of different groups of ovarian cancer cells by the EdU assay." (PMID 35101076, 2022). "TRPM7 silencing enhanced AMPK activation to shift glycolysis to oxidative phosphorylation by promoting HIF-1α ubiquitination degradation in ovarian cancer." (PMID 35101076, 2022). "To understand how HIF-1α and AMPK activation regulate the TRPM7 silencing-induced metabolic reprogramming in ovarian cancer cells, we first generated HIF-1α over-expression in TRPM7 silencing ovarian cancer cells." (PMID 35101076, 2022). "To understand how TRPM7 modulated metabolic reprogramming in ovarian cancer, we analyzed the expression of TRPM7, glycolysis-related HK2, PDK1, and OXPHOS-related IDH3B and UQCRC1 in 60 ovarian cancer tissues by IHC." (PMID 35101076, 2022). "Given that up-regulated TRPM7 expression is related to poor prognosis of ovarian cancer, we determined the impact of TRPM7 expression on cell proliferation." (PMID 35101076, 2022). "Hypoxia induced HIF-1α protein expression in ovarian cancer cells, which was very weak in the TRPM7 silencing ovarian cancer cells." (PMID 35101076, 2022).
ovarian carcinoma (continued). "To understand how TRPM7 silencing regulated gene expression in ovarian cancer cells, we performed RNA-seq analyses between SKOV3 sh-Control and SKOV3 sh-TRPM7 cells." (PMID 35101076, 2022). "For example, calcium channel TRPM7 silencing inhibited the EMT in ovarian cancer by attenuating the calcium signals." (PMID 35615675, 2022). "This study investigated the impacts of TRPM7 silencing on ovarian cancer cell proliferation, glucose metabolism and the AMPK / HIF-1α signaling." (PMID 35101076, 2022). "Consistently, PET-CT imaging revealed that treatment with carvacrol to inhibit TRPM7 activity also decreased 18F-FDG uptake by xenograft ovarian cancer in mice." (PMID 35101076, 2022). "Next, we tested how inhibition of AMPK modulated the TRPM7 silencing-promoted OXPHOS in ovarian cancer cells." (PMID 35101076, 2022). "Their former study has revealed that TRPM7 overexpression is apparently seen in ovarian cancer tissues and cells, especially in metastatic ovarian cancer tissues." (PMID 34938330, 2021). "TRPM7 expression was negatively correlated to E-cadherin expression, but positively correlated to Vimentin, N-cadherin, and Twist expression in ovarian cancer." (PMID 34901284, 2021). "We found that TRPM7 silencing dramatically reduced the levels of TRPM7 expression and the levels of [Ca2+]i in ovarian cancer cells." (PMID 30819230, 2019). "Actually, we found that BAPTA-AM further enhanced the PI3K inhibitor- or TRPM7 silencing-decreased migration, invasion and wound healing in ovarian cancer cells." (PMID 30819230, 2019). "TRPM7 expression is negatively correlated with E-cadherin, but positively with N-cadherin, Vimentin and Twist expression in ovarian cancer samples." (PMID 30819230, 2019). "In summary, up-regulated TRPM7 expression was correlated with high levels of EMT process in ovarian cancer and associated with shorter survival of patients with ovarian cancer in this population." (PMID 30819230, 2019). "Together, TRPM7 silencing inhibited the migration, invasion, wound healing of ovarian cancer cells in vitro and lung metastasis in mice." (PMID 30819230, 2019). "TRPM7 silencing inhibited the lung metastasis of implanted ovarian cancer in mice and prolonged the survival of tumor-bearing mice." (PMID 30819230, 2019). "Given that TRPM7 silencing reduced the levels of [Ca2+]i and treatment with MK886 inhibited TRPM7 expression we tested the impact of treatment with BAPTA-AM on the migration, invasion and wound healing in the TRPM7 silenced ovarian cancer cells." (PMID 30819230, 2019). "Recent TRPM7 studies on ovarian cancer have shown that TRPM7 is necessary for cancer cell growth, migration, and invasion." (PMID 30997980, 2019). "Collectively, such data demonstrated that TRPM7 silencing inhibited the EMT process in ovarian cancer cells by attenuating the calcium-related PI3K/AKT signaling." (PMID 30819230, 2019). "Further analyses indicated that the levels of TRPM7 expression were negatively correlated with E-cadherin (p = 0.0017), but positively with Vimentin ((p = 0.0107), and Twist (p = 0.0007) in ovarian cancer tissues." (PMID 30819230, 2019). "One of the predictive targets was melastatin-related transient receptor potential cation channel, subfamily M, member 7 (TRPM7), which plays a role in the inhibition of proliferation, colony formation, migration, and invasion in ovarian cancer cell lines." (PMID 30219071, 2018). "Hence, TRPM7 silencing inhibited the proliferation of ovarian cancer cells by shifting from glycolysis to OXPHOS." (PMID 35101076, 2022). "These outcomes may indicate that the glucose metabolic reprogramming in ovarian cancer is regulated by the TRPM7/AMPK/HIF-1α axis." (PMID 36844925, 2022). "Furthermore, up-regulated TRPM7 expression is positively related to pelvic lymph node metastasis and poor prognosis of ovarian cancer." (PMID 35101076, 2022). "Finally, we investigated how TRPM7 silencing decreased HIF-1α protein levels in ovarian cancer cells." (PMID 35101076, 2022).